PPP4R2 (protein phosphatase 4 regulatory subunit 2)
Description:
Regulatory subunit of serine/threonine-protein phosphatase 4 (PP4). May regulate the activity of PPP4C at centrosomal microtubule organizing centers. Its interaction with the SMN complex leads to enhance the temporal localization of snRNPs, suggesting a role of PPP4C in maturation of spliceosomal snRNPs. The PPP4C-PPP4R2-PPP4R3A PP4 complex specifically dephosphorylates H2AX phosphorylated on 'Ser-140' (gamma-H2AX) generated during DNA replication and required for DNA double strand break repair. Mediates RPA2 dephosphorylation by recruiting PPP4C to RPA2 in a DNA damage-dependent manner. RPA2 dephosphorylation is required for the efficient RPA2-mediated recruitment of RAD51 to chromatin following double strand breaks, an essential step for DNA repair.
Synonyms: PP4R2
Tractability: PROTAC: ubiquitination databases record sites on it; its protein half-life has been measured.
Gene: Protein-coding gene on chromosome 3 (72,996,803 to 73,069,198, forward strand). Ensembl gene ENSG00000163605.
Subcellular location: Cytoplasm, cytoskeleton, microtubule organizing center, centrosome; Nucleus
Subcellular location (Human Protein Atlas): Nucleoplasm
Pathways (Reactome):
DNA Repair: Processing of DNA double-strand break ends
Gene Ontology:
Molecular function: protein binding; protein phosphatase regulator activity; protein-macromolecule adaptor activity
Biological process: regulation of double-strand break repair; regulation of double-strand break repair via homologous recombination; protein modification process
Cellular component: chromatin; nucleoplasm; nucleus; protein phosphatase 4 complex; centrosome
Genetic constraint (gnomAD): Loss-of-function variants: 11 observed, 22.56 expected, observed/expected ratio (o/e) 0.49, 90% interval 0.31 to 0.81. The upper end of that interval is the gene's LOEUF score, 0.81, which puts it in group 3 of 6, group 1 being the genes least tolerant of losing a copy. Missense variants: 326 observed, 301.16 expected, observed/expected ratio (o/e) 1.08, 90% interval 0.99 to 1.19. Synonymous variants: 107 observed, 101.98 expected, observed/expected ratio (o/e) 1.05, 90% interval 0.9 to 1.23.
Homologues: Orthologues: dog PPP4R2 (94% identical), pig PPP4R2 (94% identical), guinea pig PPP4R2 (90% identical), rabbit PPP4R2 (87% identical).
Diseases named in the same sentence as PPP4R2 in open-access papers:
PPP4R2 is named in the same sentence as 18 diseases in open-access papers, as found by Europe PMC text mining. Sharing a sentence is not in itself a finding about the gene and the disease. The quoted sentences say what the papers report.
leukemia (2 papers, 2017 to 2019). A malignant (clonal) hematologic disorder, involving hematopoietic stem cells and characterized by the presence of primitive or atypical myeloid or lymphoid cells in the bone marrow and the blood. "Additional genetic alterations in the PPP4R2-deficient human myeloid leukemic cell line MEG-01 permit survival of cells that acquired genomic instability providing an advantage to select for subclones, and indicating a cooperative role for PPP4R2 deficiency in leukemia progression." (PMID 29221109, 2017). "The implication of PPP4R2 in the regulation of cell survival and DNA repair in hematopoietic and leukemia cells has been recently reported." (PMID 31142279, 2019). "Response to DNA damage upon Ppp4r2 knockdown in the murine MLLT3-KMT2A transformed leukemia model was accompanied by enhanced DNA damage and/or impaired DNA repair." (PMID 29221109, 2017). "The human myeloid leukemic cell line MEG-01 carries a homozygous deletion of PPP4R2 in addition to the heterozygous deletion of the other 3p candidate genes, which suggests a potential role of PPP4R2 in hematopoiesis and leukemia development." (PMID 29221109, 2017). "To identify a functional role of PPP4R2 in hematopoiesis and leukemia, we genetically inactivated Ppp4r2 by RNAi in murine hematopoietic stem and progenitor cells and murine myeloid leukemia." (PMID 29221109, 2017). "Hence, suppression of Ppp4r2 in the murine MLLT3-KMT2A leukemia model reduced the de-phosphorylation of key DDR proteins, which resulted in elevated DDR presenting inefficient DNA repair followed by accumulation of DNA damage." (PMID 29221109, 2017). "Additionally, qRT-PCR analyses of the other PPP4 regulatory subunits Ppp4r1, Ppp4r3a, and Ppp4r3b were performed to validate specific knockdown of Ppp4r2 in the MLLT3-KMT2A leukemia model." (PMID 29221109, 2017). "In further accordance, GEP signatures and exome sequencing of leukemias with 3p microdeletion support the disturbance of the respective pathways by low PPP4R2 expression, which might provide an advantage for subclones with 3p microdeletion." (PMID 29221109, 2017). "Knockdown of Ppp4r2 in murine MLLT3-KMT2A leukemia followed by induction of DSB was further accompanied by elevated levels of pRPA2, which is a specific and relevant substrate of the PPP4R2-containing PPP4 complex that impaired HR-mediated DSB repair by inefficient DDR." (PMID 29221109, 2017). "In the present work we report on the functional characterization of PPP4R2, one candidate gene located in the CDR, in the context of hematopoiesis and leukemia." (PMID 29221109, 2017). "Differential PPP4R2 expression in hematopoietic cells and primary AML samples prompted us to hypothesize that PPP4R2 might play a functional role in leukemia." (PMID 29221109, 2017).
lung carcinoma (2 papers, 2017 to 2019). "Genetic inactivation of PPP4R2 in the lung cancer cell line A549 displayed significant more metastatic progression in mice, indicating that lower levels of PPP4R2 support metastatic processes e.g. migration and invasion to promote tumor progression." (PMID 29221109, 2017). "Recent expression analyses of primary lung cancer cases revealed lower PPP4R2 levels in late stages of tumor progression characterized by lymph node metastases than in matched primary lung cancer tissue." (PMID 29221109, 2017).
breast carcinoma (1 paper, 2017). "Previous reports have shown that PPP4R2 depletion in MCF-7 breast cancer cells caused increased KAP1 phosphorylation in response to camptothecin- or etoposide-mediated DNA damage, and was associated with a significant reduction of NHEJ-mediated DNA repair." (PMID 29221109, 2017).
cervix carcinoma (1 paper, 2017). "Moreover, γH2AX as a readout for DNA damage has also been shown to be controlled by PPP4R2 in osteosarcoma U2OS or cervix carcinoma HeLa cell line, even independent of exogenous DNA damage." (PMID 29221109, 2017).
osteosarcoma (1 paper, 2017). A usually aggressive malignant bone-forming mesenchymal neoplasm, predominantly affecting adolescents and young adults. "In osteosarcoma cell line U2OS it has been demonstrated that PPP4R2 in complex with the catalytic subunit was able to de-phosphorylate γH2AX in a dose-dependent manner." (PMID 29221109, 2017).
spinal muscular atrophy (1 paper, 2020). A motor neuron disease that affect the muscles, and characterized by muscle weakness and atrophy resulting from progressive degeneration and irreversible loss of the anterior horn cells in the spinal cord (i.e., lower motor neurons) and the brain stem nuclei. "These researches showed that the protein product of PPP4R2 is related to a motor disorder characterized by the progressive loss of motor neurons and spinal muscular atrophy through its regulatory interaction with survival of SMN." (PMID 32664293, 2020).
Stroke (1 paper, 2023). Sudden impairment of blood flow to a part of the brain due to occlusion or rupture of an artery to the brain. "This tile also includes relevant genes that have robust expression in healthy granulocytes or neutrophils, but in stroke are more suppressed in TP3, like KREMEN1, a negative regulator of Wnt/β catenin pathway and PPP4R2, a modulator of neuronal differentiation and survival." (PMID 36803375, 2023).
thyroid cancer (1 paper, 2022). "Using a computer algorithm to identify major driver mechanisms in our PTC cohort, the results showed that, in addition to BRAF mutations, NF1, PMS2, CDC27 and PPP4R2 gene mutations are also involved in the development of thyroid cancer, and joint mutations often occur." (PMID 35865459, 2022).
cancer (3 papers, 2017 to 2023). A tumor composed of atypical neoplastic, often pleomorphic cells that invade other tissues. "In accordance, an analysis comparing CN-AML cases with 3p CDR (n = 9) with CN-AML without 3p deletion (n = 161) revealed a significant enrichment of gene sets associated with cancer, DNA repair as well as cell death and survival, which further supports a strong impact of PPP4R2 in 3p deleted AML." (PMID 29221109, 2017). "Conversely, the under-expressed protein PPP4R2 is a regulatory subunit of the protein phosphatase 4 complex (PPP4), which has been linked to tumour progression in several cancers." (PMID 37987367, 2023).
neoplasia (3 papers, 2017 to 2023). "Consistent with cell counting result, Ppp4r2 functioned as a cellular antagonist of the Sufu tumor suppressor, while PKA did as an agonist in DAOY cells, according to EdU incorporation and colony formation results." (PMID 32826873, 2020). "The role of PPP4R2 in governing PPP4 and its de-phosphorylation activity has not been investigated in myelopoiesis and associated neoplasia so far." (PMID 29221109, 2017).
PPP4R2 also shares sentences with these, for which no sentence is quoted: mastitis (2 papers); acute myeloid leukemia (1); Alzheimer disease (1); cognitive decline (1); infection (1); myeloid leukemia (1); pancreatic cancer (1); Parkinson disease (1).